MMP9 (matrix metallopeptidase 9)
Diseases named in the same sentence as MMP9 in open-access papers (continued):
Sharing a sentence is not in itself a finding about the gene and the disease.
Sepsis (continued). "In line with our data showing hyperglycemia-induced MMP-9 secretion by macrophages, an association between blood glucose levels and MMP-9 was documented in patients with sepsis, acute ischemic stroke, acute coronary syndrome, and T2D." (PMID 32806763, 2020). "Sepsis-associated lung injury is linked to elevated MMP-9 and TIMP-1 lung expression, but mechanical ventilation per se is related to reduction in MMP-9 and TIMP-1 levels." (PMID 29861795, 2018). "MMP-9, TIMP-1, and MMP-9/TIMP ratio were good diagnostic or prognostic biomarkers of sepsis after major abdominal surgery and were linked to sepsis-associated organ dysfunction." (PMID 29861795, 2018). "ROC curve analysis showed that TIMP-1 and MMP-9/TIMP-1 ratio were very good diagnostic biomarkers of sepsis after major abdominal surgery." (PMID 29861795, 2018). "In the other hands, MMP-9 also has been reported to be a useful diagnostic biomarker of the severity of sepsis." (PMID 28661460, 2017). "Recently, in a study Involving 192 Patients with severe sepsis it was observed association between TIMP1 / MMP9 ratio and mortality in a predictive model at 30 days follow-up." (PMID 28192449, 2017). "The aim of our study was to examine the clinical and pathogenic link between MMP-9 and BG levels in patients with early severe sepsis and septic shock." (PMID 27110221, 2016). "This is the first study in humans demonstrating a significant and early association between MMP-9 and BG levels in in patients with severe sepsis and septic shock." (PMID 27110221, 2016). "The objective of this study was to examine the clinical and pathogenic link between MMP-9 and blood glucose (BG) levels in patients with early severe sepsis and septic shock." (PMID 27110221, 2016). "This prospective observational study in humans demonstrates a significant and early association between MMP-9 and BG levels in patients with severe sepsis and septic shock." (PMID 27110221, 2016). "In conclusion, we report for the first time an association between the MMP-13 and the MMP-1 SNPs and sepsis, as well as an independent association of plasma MMP-8 and MMP-9 levels with sepsis." (PMID 24833564, 2014). "Nakamura and colleagues were the first to report evidence of elevated MMP-9 levels with association to mortality in sepsis." (PMID 20356362, 2010). "MMP9 demonstrated excellent diagnostic performance, with an area under the curve (AUC) of 0.9874 for distinguishing sepsis from nonsepsis patients, and also showed good performance in distinguishing sepsis from simple bacteremia (AUC = 0.9777)." (PMID 41306770, 2025). "MMP-9 was also found to be associated with delirium in ICU sepsis." (PMID 38029239, 2023). "Thus, MMP-9 levels are a useful diagnostic tool for early sepsis detection, which can then inform the subsequent intervention approach." (PMID 37622890, 2023). "Taken together, these findings suggest that pulmonary upregulation of MMP-9 may be recognized as part of a self-protective response to sepsis-associated ALI." (PMID 33628393, 2021). "In conclusion, our data indicate that MMP-9-mediated RAGE shedding limits the severity of sepsis-associated pulmonary edema, inflammation, oxidative stress, and lung injury by suppressing the RAGE/NF-κB signaling pathway via the decoy receptor activities of sRAGE." (PMID 33628393, 2021). "Our results suggest that MMP-9-mediated RAGE shedding might limit the severity of sepsis-associated lung damage by suppressing the RAGE/NF-κB signaling pathway in the lung via the decoy receptor activities of sRAGE." (PMID 33628393, 2021). "MMP-9 was also shown to be a diagnostic indicator of survival during sepsis." (PMID 33488296, 2021). "After cecal ligation and perforation in rats, which induces a model of sepsis, Evans blue leakage was MMP2 and MMP9 dependent such that inhibition of these two enzymes could reverse the clinical features of sepsis-associated encephalopathy." (PMID 34594000, 2021).
Sepsis (continued). "In conclusion, this study demonstrated that pulmonary upregulation of MMP-9 might be recognized as part of a self-protective response to sepsis-associated lung injury." (PMID 33628393, 2021). "MMP-2 and MMP-9 blocker could reverse the increase of permeability of the blood-brain barrier and improve acute cognitive alteration associated with sepsis." (PMID 31213027, 2019). "An independent association of MMP-8 and MMP-9 levels with sepsis was also observed." (PMID 24833564, 2014). "Therefore, MMP-9 may be associated with inflammatory damage to the endothelium by regulating the type of macrophage polarization in sepsis." (PMID 39199368, 2024). "We speculate that MMP9 may be a candidate diagnostic gene for ROP patients with sepsis." (PMID 38028617, 2023). "In addition, intrapulmonary knockdown of MMP-9 aggravated, whereas administration of recombinant sRAGE attenuated sepsis-associated activation of the RAGE/NF-κB signaling pathway, consequently resulting in the exacerbation or improvement of pulmonary inflammation and oxidative stress, respectively." (PMID 33628393, 2021). "In addition, MMP-9 contributes to the progression of septic-associated encephalopathy, myocardial depression and is associated with a rising blood glucose level in patients with early sepsis." (PMID 28661460, 2017). "However, others have reported that MMP-9/TIMP-1 ratios were significantly lower at the first 3 days in 38 patients with severe sepsis compared to healthy controls and that a lower MMP-9/TIMP-1 ratio was associated with greater sepsis illness severity and risk for mortality." (PMID 27089280, 2016). "This study reveals the molecular network basis of sepsis immune heterogeneity, identifying MMP9 as a key regulator of CD4+ T cell exhaustion." (PMID 41306770, 2025). "Receiver operating characteristic analysis yielded an AUC of 0.9722, highlighting MMP9 as a robust biomarker for sepsis diagnosis." (PMID 41306770, 2025). "Based on the four diagnostic genes for sepsis and two diagnostic genes for relapsed B-ALL, LTF and MMP9 were identified as two key common genes." (PMID 41007866, 2025). "Inhibition of MMP9, either through gene knockout or pharmacological inhibitors, has been shown to attenuate inflammatory responses in sepsis and improve survival." (PMID 40144662, 2025). "Although molecules such as MMP9 and PRTN3 have also been linked to sepsis prognosis, current investigations into these molecules in sepsis remain limited." (PMID 41305822, 2025). "Elevated blood serum concentrations of MMP9, MMP2, and TIMP4 are associated with a progressive course of NEC with sepsis." (PMID 40303487, 2025). "This MMP9-centered precision inhibitory strategy offers a new therapeutic avenue for overcoming sepsis-induced immunoparalysis." (PMID 41306770, 2025). "In contrast to conventional biomarkers that primarily reflect general inflammation, MMP9 stands out by directly mirroring the immunosuppressive phase of sepsis." (PMID 41306770, 2025). "In sepsis patients, serum MMP9 levels were positively correlated with sequential organ failure assessment scores." (PMID 41306770, 2025). "During sepsis, matrix metalloproteinase-9 (MMP-9) and hyaluronidase (HYAL1) activity upregulates, directly cleaving the glycocalyx; TNF-α and IL-1β inhibit glycocalyx synthase (e.g., EXTL3) via the TLR4/NF-κB pathway." (PMID 40718792, 2025). "Our findings establish MMP9 as a critical regulator of CD4+ T cell dysfunction in sepsis, acting primarily through disruption of TCR signaling and intracellular calcium homeostasis." (PMID 41306770, 2025). "It is known that MMP-2 and MMP-9 levels increase in sepsis and show a positive correlation with the severity of the disease." (PMID 39860018, 2025). "Along with these changes, the Sepsis group showed a significant 50% (p = 0.0267) increase in matrix metalloproteinases 9 (Mmp9) expression." (PMID 41315622, 2025).
Sepsis (continued). "Then, four diagnostic genes of sepsis (LTF, MMP9, S100A9, and S100A8) and two diagnostic genes of relapsed B-ALL (LTF and MMP9) were screened by SVM-RFE, respectively." (PMID 41007866, 2025). "Utilizing bioinformatic approaches, our study newly identified LTF and MMP9 as shared hub genes in pediatric sepsis and relapsed B-ALL." (PMID 41007866, 2025). "The results indicated that the expression levels of LTF and MMP9 in the relapsed B-ALL with sepsis group were significantly higher than those in the control group (p < 0.001)." (PMID 41007866, 2025). "Bulk transcriptome analysis from 10 cohorts showed that MMP9 expression levels were significantly elevated in sepsis samples compared to those in healthy controls, peaking in C1 samples." (PMID 41306770, 2025). "Differential gene expression analysis further demonstrated marked transcriptional upregulation of both LTF and MMP9 in the sepsis and relapsed B-ALL groups relative to the control group (p < 0.05), further supporting their potential as diagnostic biomarkers." (PMID 41007866, 2025). "Gene expression profiling has identified several NET-related genes—ELANE, TLR4, MPO, PADI4, CTSG, MMP9, and S100A12—as being potential diagnostic biomarkers and therapeutic targets for sepsis." (PMID 40806591, 2025). "Clinical data reveal that MMP-2 and MMP-8 are elevated in patients with severe sepsis, whereas MMP-9 shows a rapid, transient spike, linking to organ damage in septic patients." (PMID 40806591, 2025). "In recent decades, several new early biomarkers for sepsis have been tested, such as matrix metalloproteinase-9 (MMP-9), its endogenous inhibitor tissue inhibitor of metalloproteinase-1 (TIMP-1), and mid-regional pro-adrenomedullin (MR-proADM)." (PMID 38337856, 2024). "MMP-9 is elevated in patients with acute lung injury (ALI) and acute respiratory distress syndrome (ARDS), which correlates closely with lung injury severity and supports the assertion that MMP-9 plays a major role in the pathophysiology of sepsis." (PMID 37622890, 2023). "MMP9 has huge prospects as a biomarker for diagnosing sepsis with venous thrombosis and a potential molecular target for treatment." (PMID 38029239, 2023). "When comparing serum and peritoneal levels of these MMPs with sepsis score, peritoneal MMP-9 was found to hold promise as an indicator of the potential to develop sepsis in cases of colic." (PMID 36670767, 2023). "Accordingly, further study of MMP9 can provide a comprehensive understanding of its role in sepsis with VTE." (PMID 38029239, 2023). "Elevated peritoneal fluid MMP-9 concentrations correlated with the development of sepsis and endotoxemia in colic cases." (PMID 36670767, 2023). "As MMP plays an important role in invasionof inflammatory cells by degrading the extracellular matrix, significantly higherlevels of MMP-9 was reported in acute phase KD than in sepsis with significantlydecreased level through convalescent phase." (PMID 39076265, 2023). "MMP9 shows promise as a biomarker for diagnosing sepsis with venous thrombosis and a potential molecular target for treating this patient population." (PMID 38029239, 2023). "A comprehensive analysis was conducted to investigate the impact of senescence-related genes on sepsis, and 8 hub genes (IGFBP7, GMFG, IL10, IL18, ETS2, HGF, CD55, MMP9) associated with senescence were identified." (PMID 38259686, 2023). "The cell walls of Gram-negative bacteria lipopolysaccharide (LPS) have been shown to induce the release of MMP-9 via neutrophils and monocytes in sepsis patients." (PMID 37622890, 2023). "Treatment with MMP-2 and MMP-9 inhibitors or MMP-2 or MMP-9-specific inhibitors in a rat model of sepsis reversed MMP-induced cognitive changes to BBB permeability, brain inflammatory responses, and sepsis." (PMID 36445634, 2023).
Sepsis (continued). "In this study, we present and test a paper-based sensing platform to detect MMP-9 for the first time as a biomarker for sepsis using a fecal intraperitoneal (FIP) approach in a live mouse model." (PMID 37622890, 2023). "Mmp9 is a commonly induced gene among the MMPs in both models of sepsis, and previous studies have reported its upregulation in the liver of CLP-induced septic rats." (PMID 37510271, 2023). "Peritoneal fluid MMP-9 concentrations are preferable over plasma for the identification of sepsis and endotoxemia in colicking horses." (PMID 36670767, 2023). "The protein expression of MMP9 in mice with sepsis and DVT was significantly higher than in the control group, which was further validated during the IHC assay conducted on venous wall samples." (PMID 38029239, 2023). "Our work adds evidence to the assertion that MMP-9 is a reliable biomarker for the detection of sepsis at early stages." (PMID 37622890, 2023). "In conclusion, our study suggests that MMP9 plays an important role in venous thrombogenesis events in sepsis." (PMID 38029239, 2023). "The compound was found to suppress the overexpression of MMP-9, IL-1β, IL-6 and iNOS induced in LPS-induced sepsis mouse models and the TC-1 cell line in a dose-dependent manner." (PMID 36588685, 2022). "4-OI protects multiple organ dysfunction in sepsis by acting on hub genes, and MMP9 is a reliable gene for the prognosis and diagnosis of sepsis." (PMID 36406124, 2022). "Earlier, MMP-9 was reported to be a biomarker in severe sepsis patients, and can also serve as a biomarker for the severity of sepsis in pediatric patients." (PMID 35205254, 2022). "The analysis showed that NOS3, SIRT1, HSP90AA1, MMP9, MMP2, PTPRC, and TLR2 were associated with multiple organ damage in sepsis." (PMID 36406124, 2022). "GPs of MMPs and TIMP (namely MMP-1 rs1799750, MMP-3 rs3025058, MMP-8 rs11225395, MMP-9 rs2234681, and TIMP-1 rs4898) have been compared in 1058 patients with suspected sepsis to assess the association with susceptibility and etiology of sepsis." (PMID 35204780, 2022). "Previous studies have proved that MMP9 is upregulated in sepsis patients compared with healthy people, and MMP9 expression can be used as a prognostic biomarker of sepsis." (PMID 35190763, 2022). "Matrix metallopeptidase 9 (MMP9) and Complement C3a Receptor 1 (C3AR1), immune infiltration-associated biomarkers of sepsis, have been reported to be related with the prognosis of sepsis patients." (PMID 35265105, 2022). "First, Matrix Metallopeptidase 9 (MMP9) was found to be one of the differentially expressed genes involved in the pathogenesis of sepsis." (PMID 36032067, 2022). "Differential analysis of HSP90AA1, MMP2, and MMP9 in the sepsis spleen injury-control group (SSp-C) showed that the p-value were all <0.05, indicating differential expression." (PMID 36406124, 2022). "In fact, the eventual mortality of patients has been associated with the elevated levels of MMP‐2, MMP‐9, MMP‐8, and TIMP‐1, as observed in the early stages of sepsis." (PMID 35818743, 2022). "MMP-9 has previously been shown to be released in the inflammatory process in sepsis, cardiovascular disease and AP." (PMID 35157709, 2022). "In the present study, we found that intrapulmonary knockdown of MMP-9 significantly decreased sRAGE release and enhanced sepsis-induced activation of the RAGE signaling pathway in lung tissues." (PMID 33628393, 2021). "In this study, we aimed to evaluate the diagnostic value of several MMPs (MMP-2, MMP-9, MMP-8) and TIMPs (TIMP-1 and TIMP-2) for equine colic, which is often associated with endotoxemia and sepsis in case of strangulating obstruction." (PMID 33488296, 2021). "We collected PBMCs from septic patients to detect the relationship between MMP-9 gene expression with the severity of sepsis in patients and found MMP-9 mRNA levels have a positive correlation with APACHE III score." (PMID 33431821, 2021).
Sepsis (continued). "To evaluate the MMP-9 expression in the lung of septic mice, we analyzed the gene expression profiles of mouse sepsis-induced lung injury datasets GSE15379, GSE52474, and GSE60088." (PMID 33628393, 2021). "Pulmonary MMP-9 knockdown also decreased sRAGE release and enhanced sepsis-induced activation of the RAGE/nuclear factor-κB (NF-κB) signaling pathway, meanwhile aggravating sepsis-induced oxidative stress and inflammation in lung tissues." (PMID 33628393, 2021). "We then investigated the effect of pulmonary knockdown of MMP-9 on sepsis-induced oxidative stress and inflammation." (PMID 33628393, 2021). "The MMPs and their inhibitors have been associated with mortality in organ injury and sepsis, where serum levels of TIMP‐1 and TIMP-1/MMP‐9 ratios have been associated with disease severity and mortality." (PMID 31932967, 2021). "Taken together, these results indicate that pulmonary knockdown of MMP-9 aggravates sepsis-induced oxidative stress and inflammation in lung tissues." (PMID 33628393, 2021). "Using a CLP-induced sepsis model, it was observed that both mRNA and protein expression levels of MMP-9 in lung tissues were increased in the CLP group compared to the sham group." (PMID 33628393, 2021). "Nevertheless, we decided to go on with the overall scoring to have the best statistical power when evaluating the regression of MMP-9 concentrations in plasma or peritoneal fluid and sepsis scoring." (PMID 33488296, 2021). "As pediatric sepsis severity increases, the levels of MMP9 and MPO decreased significantly (P < 0.05)." (PMID 33748037, 2021). "Using a MMP-9 concentration of >113 ng/ml in the peritoneal fluid was found to be the ideal cutoff to identify positive sepsis scoring (≥10/19 points; sensitivity of 83.3% and specificity of 82.9%)." (PMID 33488296, 2021). "We then examined the effects of MMP-9 knockdown and sRAGE on sepsis-induced pulmonary inflammation, oxidative stress, and the related signaling pathways." (PMID 33628393, 2021). "In conclusion, MMP-9 concentrations were increased in plasma and peritoneal fluid of horses presenting with colic and scoring positive for sepsis." (PMID 33488296, 2021). "ROC analyses were used to find the optimal cutoff of MMP-9 as well as TIMP-1 concentrations to identify animals with positive sepsis scoring (≥10/19 points)." (PMID 33488296, 2021). "By contrast, the MMP9 levels in the model system were far above the concentrations described in sepsis as early as 1 h after incubation." (PMID 33178198, 2020). "Further qRT-PCR validation indicated that four genes are differentially expressed between patients with sepsis and healthy subjects (MMP9, S100A8, S100A9, and ANXA3)." (PMID 32922168, 2020). "In a mouse model, MMP-9 deficiency results in resistance to endotoxin shock, suggesting that MMP-9 is important in sepsis." (PMID 33162790, 2020). "As seen in whole blood samples from sepsis patients, TLR2 induction correlated with the overexpression of genes associated with immunosuppression (IL10, FPR2) or wound healing (MMP9)." (PMID 31396208, 2019). "MMP-9 activation plays also a role in amniotic membrane rupture during labor and enhanced MMP levels were associated with sepsis." (PMID 30897723, 2019). "Further, MMP-9 blockade attenuated blood-brain-barrier dysfunction in a cecal ligation and puncture rat model of sepsis." (PMID 31213027, 2019). "The association of MMP-9 and TIMP-1 with severity and outcome of sepsis has already been recognised." (PMID 29861795, 2018). "The evaluation of MMP-9, TIMP-1, and MMP-9/TIMP-1 ratio as diagnostic biomarkers of sepsis was performed by the calculation of AUC-ROC values." (PMID 29861795, 2018). "The role of matrix metalloproteinase-9 (MMP-9) and tissue inhibitor of matrix metalloproteinase-1 (TIMP-1) in sepsis after major abdominal surgery and sepsis-associated organ dysfunction is unexplored." (PMID 29861795, 2018).